MAP2K2 (mitogen-activated protein kinase kinase 2)
Diseases named in the same sentence as MAP2K2 in open-access papers (continued):
Sharing a sentence is not in itself a finding about the gene and the disease.
Intellectual disability (3 papers, 2015 to 2025). "Specifically, in terms of neurodevelopmental functions, patients with mutations in the MAP2K2 gene show a lower incidence of intellectual disability (ID) compared to those with mutations in other genes, such as BRAF and MAP2K1, with an incidence rate of only 25%." (PMID 39982946, 2025). "MAP2K1 variants are correlated with skeletal deformities and motor dysfunction, and MAP2K2 and KRAS variants are correlated with mild intellectual disability." (PMID 37697378, 2023). "This cluster comprises of a selection of genes that have been associated previously with intellectual disability, such as YWHAE, SOS1, and MAP2K2, and several whose function makes them likely candidates for involvement in ID." (PMID 25781962, 2015).
leukemia (3 papers, 2011 to 2025). A malignant (clonal) hematologic disorder, involving hematopoietic stem cells and characterized by the presence of primitive or atypical myeloid or lymphoid cells in the bone marrow and the blood. "Among our study cohort, two siblings, one with syndromic leukemia (case #3) and one with Hodgkin’s lymphoma, were homozygous for the MAP2K2 variant." (PMID 40995433, 2025). "However, the same effect on splicing could not be observed for MAP2K2, VEGF or FAS in leukemia or HeLa cells, suggesting that different tumor lineages may respond differently to SRPK inhibition." (PMID 26244849, 2015).
multiple myeloma (3 papers, 2018 to 2024). "YTHDF2 was identified to promote multiple myeloma cell proliferation via STAT5A/MAP2K2/p-ERK axis." (PMID 37256443, 2024). "In multiple myeloma cells, YTHDF2 sustains proliferation through the STAT5A/MAP2K2/p-ERK pathway, while in lung adenocarcinoma cells, it promotes proliferation by targeting the AXIN1/WNT/β-catenin signalling pathway." (PMID 38397033, 2024).
atherosclerosis (2 papers, 2023 to 2025). A disease characterized by the build-up of fatty material and calcium deposition in the arterial wall resulting in partial or complete occlusion of the arterial lumen. "Together, the results from our studies in ApoE-/- mice validated that lnc_000048 promoted atherosclerosis by activating the lnc_000048/MAP2K2/ERK axis." (PMID 36689133, 2023). "Our results indicated how lnc_0000048 promoted atherosclerosis and provide new potential strategies to target the lnc_000048 /KDM1A/MAP2K2/ERK axis to inhibit the progression of atherosclerosis." (PMID 36689133, 2023). "Atherosclerosis develops in large part as a result of the MAPK pathway, and our research found that the expression level of MAP2K2 was elevated during atherosclerosis development." (PMID 36689133, 2023). "Lnc000048 regulates the expression of MAP2K2 (mitogen-activated protein kinase 2) by inhibiting the demethylation activity of LSD1 to promote the phosphorylation level of ERK and ultimately affects the atherosclerosis process in mice." (PMID 40028036, 2025). "Furthermore, upregulated lnc_000048 indirectly regulated ERK phosphorylation by MAP2K2 and eventually activated the inflammatory response through the MAPK pathway, which was involved in atherosclerosis." (PMID 36689133, 2023).
autism (2 papers, 2012 to 2024). Persistent deficits in social interaction and communication and interaction as well as a markedly restricted repertoire of activity and interest as well as repetitive patterns of behavior. "Our identification of rare damaging variants in the HRAS and MAP2K2 genes further suggests that dysregulation of the Ras/ERK pathway may contribute to autism risk." (PMID 22558107, 2012).
epilepsies (2 papers, 2023).
liver cancer (2 papers, 2021 to 2025). An epithelial or non-epithelial malignant neoplasm that arises from the liver. "Our study shows that high expression of MAP2K2 can predict the occurrence of liver cancer and is positively correlated with tumor progression, but it may not be suitable as a prognostic marker." (PMID 40587753, 2025).
ovarian carcinoma (2 papers, 2007 to 2022). A malignant neoplasm originating from the surface ovarian epithelium. "We further performed correlation analysis of GPR12 mRNA level with ERK1/2 cascade expression including MAP3K1, MAP2K1, MAP2K2, and MAPK1 by using ovarian cancer data from TCGA database." (PMID 35903681, 2022).
prostate carcinoma (2 papers, 2010 to 2020). A carcinoma that arises from epithelial cells of the prostate gland. "For example, AR, EGFR, DDR2 and MAP2K2 were connected with mtDNA genes in prostate cancer, and TMPRSS2, NF1, PIK3CA, BRCA1 and TOP1 were the top neighbors of mtDNA genes in multiple cancer types." (PMID 32024997, 2020).
acute lung injury (1 paper, 2025). A condition of lung damage that is characterized by bilateral pulmonary infiltrates (pulmonary edema) rich in neutrophils, and in the absence of clinical heart failure. "MAP2K1 and MAP2K2, integral to the MAPK/ERK signaling pathway, have been shown to regulate inflammation and interferon responses, with MAP2K2 deactivation promoting the resolution of acute lung injury (ALI)." (PMID 40703672, 2025).
basal cell carcinoma (1 paper, 2022). A carcinoma involving the basal cells. "At 36 dpi, 19 potential target mRNAs (e.g., tcf7l2, hpas, and map2k2) of six DEmiRNAs were associated with five enriched KEGG pathways (e.g., basal cell carcinoma, melanogenesis, and microRNAs in cancer)." (PMID 36230377, 2022).
central nervous system lymphoma (1 paper, 2025). "The MAP2K2 variants were detected in primary central nervous system lymphoma." (PMID 40995433, 2025).
cocaine addiction (1 paper, 2023). "Upstream non-key genes (FGF2, VEGFA, and IL1B) affect the expression of downstream genes in this pathway, while MAP2K2 regulates ERK through phosphorylation, thereby affecting cocaine addiction." (PMID 37469839, 2023).
dementia (1 paper, 2012). Loss of intellectual abilities interfering with an individual's social and occupational functions. "Two key proteins in the MAPK pathway, MAP2K2 (MEK2) and MAP2K4 (JNK), were also further validated by western blotting analysis using 4 samples from HAD and 4 samples from HIV non-dementia group, respectively." (PMID 23190615, 2012).
diabetes (1 paper, 2022). "Circulating EVs from people with diabetes carry increased levels of specific phosphorylated kinases (i.e., AKT1, GSK3B, LYN, MAP2K2, MYLK, and PRKCD) and could potentially distribute activated kinases systemically." (PMID 35628588, 2022).
dyschromatosis universalis hereditaria (1 paper, 2017). A pigmentation disease characterized by reticulate hyper- and hypo-pigmentated macules in a generalized distribution.
HIV-1 infection (1 paper, 2024). The type species of lentivirus and the etiologic agent of acquired immunodeficiency syndrome (AIDS). "In the gene-pathway connections, multiple molecules and kinases for NF-κB signaling (e.g., IKBKB, JUN, FOS, MAP2K2, NFKBIA, TLR4) connected the HIV-1 infection and other inflammatory or anti-viral pathways." (PMID 39283947, 2024). "The MEK2 protein kinase (MAP2K2) molecule, involved in the mitogen-activated protein kinase (MAPK) pathway, also serves as the key molecule connecting cellular senescence and toll-like receptor (TLR) signaling with HIV-1 infection." (PMID 39283947, 2024).
Hodgkins lymphoma (1 paper, 2025). A heterogeneous group of malignant lymphoid neoplasms of B-cell origin characterized histologically by the presence of Hodgkin and Reed-Sternberg (HRS) cells in the vast majority of cases. "The LP MAP2K2 c.907C>T p.R303C and LP BMP6 c.1007G>A p.Gly336Glu variants were detected in B-ALL index case #3 and his brother with Hodgkin’s lymphoma." (PMID 40995433, 2025). "Case #3, who had B-ALL, had variants of both the MAP2K2 and BMP6 genes, which were also detected in his brother, who had Hodgkin’s lymphoma." (PMID 40995433, 2025).
invasive breast carcinoma (1 paper, 2023). A carcinoma that infiltrates the breast parenchyma. "IRF5, MAP2K2 (MEK2), and ZBTB7B were significantly overexpressed (p < 0.05) in invasive breast cancer blood samples but not in DCIS blood samples." (PMID 37445737, 2023).
kidney cancer (1 paper, 2024). Primary or metastatic malignant neoplasm involving the kidney. "Moreover, CDK4, EGFR, and MAP2K2 exhibited moderately high expression levels in cancer cells, with drugs targeting such therapeutic molecules presenting encouraging results in cancer therapy, but their clinical applications in kidney cancer are rarely reported." (PMID 38944814, 2024).
Lymphatic Metastasis (1 paper, 2025). Transfer of a neoplasm from its primary site to lymph nodes or to distant parts of the body by way of the lymphatic system. "In patients with lymphatic metastasis N1, MAP2K2/7 were high expressed (P < .05)." (PMID 40587753, 2025).
malaria (1 paper, 2013). Malaria is a serious and sometimes fatal disease caused by a parasite that commonly infects a certain type of mosquito which feeds on humans. "Gene expression levels were greater than two-fold change in acute febrile malaria including: Fc alpha receptor, Fc gamma receptor 3B, Fc epsilon receptor 1G, PI3K, MAP2K2, Arf6, KLRC3, KIR3DL2, and CEBP gamma (range two- to four-fold)." (PMID 24188121, 2013).
meningioma (1 paper, 2025). A generally slow growing tumor attached to the dura mater. "Additionally, there were eight kinases that were not significantly differently expressed between meningioma and VS present in the macrophages (LCK, PDGFRB, FGFR1, FLT1, CSK, MEK, MAP2K2, and ERBB2)." (PMID 41437121, 2025).
myeloid leukemia (1 paper, 2025). A clonal proliferation of myeloid cells and their precursors in the bone marrow, peripheral blood, and spleen. "Third, integrative analysis identified 570 genes upregulated at both the eccDNA and mRNA levels, including myeloid leukemia drivers (FLT3, RUNX1, CD33) and oncogenes (MAP2K2/3, LINC00539), mirroring the “eccDNA–oncogene amplification” axis observed in solid tumors." (PMID 41278279, 2025).
Obesity (1 paper, 2017). Accumulation of substantial excess body fat. "miR-148a might modulate fat deposition by targeting MAPKAPK5, MAPK3, and MAP2K2, and miR-148 has been shown to affect obesity and modulates adipocyte differentiation." (PMID 28293627, 2017).
omphalocele (1 paper, 2020). Omphalocele is an embryopathy classified in the group of abdominal celosomias and is characterized by a large hernia of the abdominal wall, centered on the umbilical cord, in which the protruding viscera are protected by a sac. "Similarly, inactivating Mek1 (also known as Map2k1) in a Mek2 (Map2k2) null background with a mesenchyme-specific Cre resulted in omphalocele." (PMID 32907848, 2020).
pancreatic adenocarcinoma (1 paper, 2023). "Three genes (MAP2K2, RAC3, and PAK4) that were conserved in the SSCs of all three primates were also involved in numerous pathways, including “Pancreatic adenocarcinoma pathway”, “Integrin-mediated Cell Adhesion”, “Regulation of Actin Cytoskeleton”, and “Ras signaling”." (PMID 36902187, 2023).
Parkinson disease (1 paper, 2021). A progressive degenerative disorder of the central nervous system characterized by loss of dopamine producing neurons in the substantia nigra and the presence of Lewy bodies in the substantia nigra and locus coeruleus. "Corynoxine can regulate several kinases, including RPS6KB1, MAP2K2, and PLK1, contributing to the clearance of AD-associated β-amyloid precursor protein (APP) and Parkinson disease-associated α-synuclein." (PMID 33807157, 2021).
renal carcinoma (1 paper, 2025). A carcinoma arising from the epithelium of the renal parenchyma or the renal pelvis. "Differential expression analysis revealed that MAP2K2 expression level was significantly higher in renal cancer tissues compared to normal tissues." (PMID 39781472, 2025).
respiratory infections (1 paper, 2025). "One potential therapeutic strategy to combat respiratory infections and inflammation has been developed from understanding the functional roles of mammalian serine threonine protein kinases Map2k1 (MEK1) and Map2k2 (MEK2)." (PMID 40422262, 2025).
sarcoma (1 paper, 2023). A usually aggressive malignant neoplasm of the soft tissue or bone. "Multiple genes were downregulated (p < 0.05) in sarcoma tumors, including HSP90AB1, IGHA1, INSM1, IRF5, MAP2K2, and SEH1L." (PMID 37445737, 2023).
cancer (63 papers, 2010 to 2025). A tumor composed of atypical neoplastic, often pleomorphic cells that invade other tissues. "MAP2K2, one of the core drivers of cancer, encodes mitogen-activated protein kinase kinase 2 (MEK2) which plays a key role in mitogenic growth factor signaling, and knockdown of MEK2 inhibits the invasive ability of PAAD cancer cells." (PMID 37822927, 2023). "Exemplary cases include ncORFs in the cancer hallmark genes CREBBP, CRTC1, CSF3R, FGFR2, IKZF1 and MAP2K2 with peptide support in all but two of the analyzed cancer types." (PMID 37275273, 2023). "The patterns of 3 differentially expressed immune-associated CRGs, MAP2K2, SOD1, and VEGFA, in 3 single-cell samples of normal tissues adjacent to cancer were further analyzed as controls." (PMID 37822927, 2023). "In this study, we discovered that RIPK2 interacts with six protein kinases: MKK7 (MAP2K7), DNA-PKcs (PRKDC), RSK2 (RPS6KA3), MST4 (STK26), MEK2 (MAP2K2), and CSK (CSK), many of which were implicated in cancer metastasis." (PMID 35115556, 2022). "Of note, an altered kinase signaling network involving EGFR, PDGFR, PAK1, PTK2 (FAK), PRKCD, and MAP2K2 appear to regulate the aberrant changes in the cancer cells and the TME accompanying recurrence." (PMID 35919862, 2022). "A comparison of genome-wide methylation profiles of NHK and cSCC cell lines revealed a statistically significant difference in methylation in 361 unique genes (adjusted p-value ≤ 0.01), including known cancer drivers (MAP2K2, WNT5A, COL4A1, BMP2 and FGF7)." (PMID 31336867, 2019). "Of the remaining 17 variants, all but three are accounted for by six genes (BRAF, CBL, MAP2K1, MAP2K2, RAF1, and SOS1) encoding members of the RAS-MAPK pathway, among which nine variants have previously been reported in either congenital disorders or cancer." (PMID 30355600, 2018). "Germline mutations (CARS or MAP2K2 mutation) were detected in 2 patients without cancer history and the relationship between tumor development and hereditary should be considered, but data were limited, further data were needed to investigate it." (PMID 37664545, 2023). "Using the Oncomine database, we compared MAP2K transcription in 20 cancers and normal tissues: mRNA expression of MAP2K1/3/4/6 was significantly lower, and MAP2K2 was significantly higher, in LIHC tissue (P < .05)." (PMID 40587753, 2025). "But single-cell sequencing analysis showed that MAP2K2 was significantly more expressed in NK and CMP cell subsets in normal pancreatic tissues adjacent to cancer than in PAAD tissues." (PMID 37822927, 2023). "From the lncRNA-mRNA pathway network, PYCARD, RIPK2, and CASP1 were found to be significantly enriched in the NOD-like receptor signaling pathway, whereas MAP2K2, LUM, RPS6, PDCD4, TWIST1, and HIF1A were significantly enriched in proteoglycans in cancers." (PMID 36619896, 2022). "For example nocodazol, a colchicine binding site agent was found to simultaneously inhibit various cancer-related kinases, including ABL1, c-KIT, BRAF, MEK1 (MAP2K1), MEK2 (MAP2K2), and MET." (PMID 33671106, 2021). "For patient ID 110, this notably included MAP2K2, KIT, VEGFA, A2M, ICAM1 and PLA2G4A, all of which are involved in cancer development." (PMID 34771574, 2021). "Moreover, the pathway genes with most links to the query set: MAPK1, MAP2K1, YWHAB, MAP2K2 and MAPK3 are known to be highly expressed in various sorts of cancer, which further highlights the connection to this cancer-derived query set." (PMID 35266519, 2022). "Taken together, these results suggest that MAP2K2, LUM, RPS6, PDCD4, TWIST1, and HIF1A may play important roles in DMD pathophysiology by regulating the MAPK pathway and proteoglycans in cancer." (PMID 36619896, 2022). "In our proposed DMD-related lncRNA-mRNA pathway networks, PYCARD, RIPK2, and CASP1 were significantly enriched in the NOD-like receptor signaling pathway, whereas MAP2K2, LUM, RPS6, PDCD4, TWIST1, and HIF1A were significantly enriched in proteoglycans in cancers." (PMID 36619896, 2022).
cancer (continued). "Of note, four of the cancer genes present in the network (MAP2K2, E2F1, FZD2, and WNT7B), although absent from our high-confident list of CIRBP targets, are enriched in CIRBP IPs." (PMID 33172965, 2021). "These genes included well-known cancer-promoting factors, such as EGFR, WNT9A, and MAP2K2." (PMID 34272396, 2021). "We speculate that the main reason for the difference in MAP2K2 transcriptome data does not lie in the cancer cells in the tissues, but in the NK cells in the TIME." (PMID 37822927, 2023).